CXCR3 (C-X-C motif chemokine receptor 3)
Diseases named in the same sentence as CXCR3 in open-access papers (continued):
Sharing a sentence is not in itself a finding about the gene and the disease.
tumor (continued). "CXCR3+ T cells and NK cells recruited to the TME by IL-18 and IP-10/CXCL10 are unlikely to possess anti-tumor function, although they are active in IFNγ production." (PMID 33718235, 2021). "Expression of CXCR3 and lack of PD-1 in CD62L+ cells were commonly observed in tumor infiltrating polyclonal T cells." (PMID 32845913, 2020). "In this context, CXCR3 was required for improving the intratumoral CD8+ T cell response, but not for the CD8+ T cell migration into the tumor." (PMID 31557787, 2019). "However, in another HCC model as well as in a triple-negative breast cancer model, the tumor-suppressive effect of sitagliptin could not be traced back to the CXCR3 chemokine cleavage, but was instead dependent on a CCL11-mediated higher eosinophilic infiltration." (PMID 31482487, 2019). "In all our cases, lymphocytes intermingled between tumor cells and in tumor stroma were deactivated (negative for activation markers CD25, CD28, CXCR3, CCR6), thus not attacking tumor cells." (PMID 29520483, 2018). "Our data showed a numerical, but not statistically significant decrease, in tumor CXCR3+ CD4+ and CD8+ T lymphocytes, whereas CCR4+ CD4+ and CD8+ T lymphocytes were present at equal frequencies in tumor and in unaffected tissue." (PMID 29020986, 2017). "For example, the tumor supernatants contained low levels of CXCL9, CXCL10 and CXCL11 (data not shown) that bind to CXCR3, a chemokine receptor known to be upregulated on NK cells upon activation and expansion." (PMID 28923105, 2017). "Our data suggests that NLGP mediated upregulation of CXCR3/CCR5 is specific for T cells, not for tumor cells." (PMID 23326300, 2013). "Moreover, tumor‐bearing mice lacking the CXCL9 receptor CXCR3 show poor responses to anti‐PD1 treatment, suggesting that CXCL9 production by cDC1s is essential for facilitating the tumor immune response." (PMID 40667699, 2025). "Importantly, despite normal influx of OT-1 T cells and other immune subsets, combination treatment in CXCR3 KO mice failed to induce durable responses, thereby implying that the influx of endogenous CD8 T cells was essential for the anti-tumor response." (PMID 38167722, 2024). "In contrast, CCL5, CXCL9, and CCL10 were upregulated in the low-risk group; high expression levels of CXCL9 and CXCL10 were correlated with improved OS in most tumors, and anti-PD1 therapy was not beneficial in CXCR3−/− (receptor of CXCL9 and CXCL10) tumor-bearing mice." (PMID 35795712, 2022). "However, in another study, CAR T cells constitutively secreting CXCL11 do not increase infiltration of CXCL11-producing, CXCR3+ CAR T cells into the tumor, although they increase the concentration of CXCL11 within tumor stromata." (PMID 36366354, 2022). "However, CXCR3 blockade significantly reduced CD8+ T cell infiltration, but not CD4+- or γδ T cell infiltration, into tumours." (PMID 33925140, 2021). "In silico criteria for tumor selection may include the presence of GM-CSF, IL-3 and FLT3-L, ligand expression of chemokine receptors CXCR4, CCR7, and CXCR3 and the absence of very high GM-CSF level." (PMID 33013879, 2020). "Importantly, knockdown of Cxcr3 in our B16F10-luc system only affected metastasis and did not affect primary tumor growth." (PMID 29050279, 2017). "However, the scarcity or absence of CXCR3+ cells in most cases means that TH1-mediated inflammation did not explain the accumulation of inflammatory cells in the stroma and at the tumour margin." (PMID 24961933, 2014). "Considering the body of evidence highlighting a favorable prognosis for cancers expressing these IFN-γ induced chemokines, disruption of the CXCR3 and/or CCR5 pathways to prevent Treg accumulation in tumors is unlikely to be effective for promoting tumor immunity." (PMID 23874342, 2013).
tumor (continued). "However, the authors speculated that this phenomenon was likely due to a homeostatic defect rather than to a CXCR3-dependent effect, although no changes in the numbers of tumor-infiltrating CD4+ and CD8+ cells in the tumor was observed." (PMID 38104126, 2023). "We show here that Cxcr3 is not a principal mechanism governing T cell migration into PDA and raise the possibility that other chemokine receptors may play a role in guiding antitumor T cells into the tumor bed." (PMID 36472588, 2023). "In part, the lack of toxicity may be due to CXCR3‐expressing CAR T cells being unable to efficiently home and infiltrate into the cerebellum, as the cerebellum expressed negligible levels of Cxcl9 and Cxcl10 when compared to the HER‐2‐E0771 tumours." (PMID 31803974, 2020). "Secondly, tumor regression could be conditioned by CD8+ T cell/myeloid cell interactions taking place in tumor-draining lymph nodes, a phenomenon not expected to be affected in CXCR3 KO mice." (PMID 26337837, 2015).
infection (327 papers, 2007 to 2026). The state of being infected such as from the introduction of a foreign agent such as serum, vaccine, antigenic substance or organism. "CXCR3 induced the proliferation of type Th1 cells, which were pro-inflammatory cells, and mediated the migration of immune cells to the site of infection, thus causing lymphocyte infiltration." (PMID 39351494, 2024). "CXCL10 binds to the chemokine receptor CXCR3, which is expressed by Th1 cells, and induces lymphocytes to migrate to the infection site, causing lymphatic infiltration and local immune response." (PMID 36034715, 2022). "The reduction in migration of CXCR3-expressing CD8+ T cells into the cerebellum was the main cause for CXCR3KO mice displaying increased mortality rates following infection with WNV." (PMID 36704563, 2022). "Among the genes whose upregulation during infection was impaired by CXCR3-deficiency, overrepresented GO terms were associated with inflammatory responses and cytokine production." (PMID 34835465, 2021). "IL-6 and IL-12p40 production from microglia were both highly upregulated during infection with T. gondii, but CXCR3 deficiency significantly decreased the concentrations of these cytokines by 54% and 42%, respectively." (PMID 34835465, 2021). "Among the genes whose upregulation during infection was impaired by CXCR3-deficiency, overrepresented GO terms were associated with immune responses and categories associated with stress responses." (PMID 34835465, 2021). "The CXCR3 expression was found to be associated with fold change of MuV-specific T-cell frequencies over time after infection." (PMID 34960178, 2021). "Our finding corroborate with the studies performed with Toxoplasma gondii and Herpes virus models, where, CXCR3-deficient mice die after infections with those pathogens." (PMID 32574175, 2020). "In our study, we observed that the total numbers of CD8 T cells as well as ZIKV-specific CD8 T cells were significantly reduced in the CNS of CXCR3-deficient mice on day 2 post i.c. infection." (PMID 32973802, 2020). "Together with our finding that CXCR3 substrates are cleaved by L. major, this suggests that one of the goals of vaccine development should be to overcome parasite-encoded CXCR3 escape upon secondary infection." (PMID 31440475, 2019). "CXCR3-deficient mice on a BALB/c background had improved control of M. tuberculosis in the lungs at chronic stages of infection." (PMID 30899256, 2019). "In general, we have demonstrated that anti-CXCR3 treatment increased the susceptibility of immunized A/Sn mice, which died very quickly due to infection." (PMID 31356587, 2019). "Our data also indicate that CXCR3 expressed on other cell types associated to IFN-γ production also influences infection." (PMID 29552679, 2017). "While infection caused a significant increase in the frequency of CXCR3+ CD4+ and CD8+ T cells in the spleen of control mice, bpV(phen) treatment completely abrogated the upregulation of CXCR3 on T cells following infection." (PMID 28710387, 2017). "cDCs and CD4+ T cells in the spleen were analyzed on day 3 post-infection to determine if the cause of the attenuated expression of CXCR3 on CD4+ T cells was due to an early defect in activation or to impaired differentiation." (PMID 25768944, 2015). "While all wild-type (WT) mice survived acute infection with 30 cysts, Cxcr3−/− animals displayed increased susceptibility with nearly 75% of mice dying by 2 weeks post-infection." (PMID 24130498, 2013). "For instance, female T cells can express more CD40LG or CXCR3, both of which are X-linked, and are generally more responsive to activation, produce more effector molecules like IFNγ in response to infection, and generate more short-lived effector cells than male-derived T cells." (PMID 40143355, 2025). "Thus, L. major-infected CXCR3-/- mice are more susceptible to infection due to a reduced number of CD4+T cells producing IFNγ in the lesion." (PMID 38709823, 2024).
infection (continued). "In cases of infection with Toxoplasma gondii, which is closely related to the intracellular protozoan parasite N. caninum, CXCR3 deficiency results in the loss of ability to control intestinal infection, increased brain parasite burden, and severe embryonic damage in a pregnant model." (PMID 36704563, 2022). "CXCR3 plays a pivotal role in mobilizing cells in response to a chemical signal, often associated with pathological conditions, wherein immunocompetent cells are drawn to infection sites." (PMID 35794867, 2022). "However, we did not observe reduced production of granzyme B. Similarly, Hickman and colleagues, showed that specific CD8+ T cells from CXCR3-deficient mice had reduced cytotoxicity when compared to control group during the infection with vaccinia virus model." (PMID 32574175, 2020). "Altogether, these results suggest that a multifactorial model of chemokine receptor directed recruitment into the DLN where CXCR3 may play a more prominent role during high inflammatory or high pathogenic infection conditions." (PMID 29719539, 2018). "Indeed, the loss of CXCR3 expression on CD8 T cells led to accelerated movement within the infection foci." (PMID 27790220, 2016). "As expected, CXCR3-deficient animals were highly susceptible to infection." (PMID 24130498, 2013). "Indeed CXCR3 and its ligands are significantly upregulated in the brain at a timepoint associated with significant T cell influx into the CNS following infection with ∼35% of T cells expressing CXCR3." (PMID 23209401, 2012). "Meanwhile, CXCR3 activation contributes to autophagy suppression and the concomitant effects of antiretroviral therapy, and this implies that CXCR3 activation is the missing link between infection and autophagy impairment associated with synaptic injury and neuronal loss." (PMID 36611975, 2023). "Despite contributing minimally to the overall pool of HIV-infected cells, CXCR3+ Tfh had the highest rate of infection by S4/5 of AHI, when they also had a significant increase in proliferation." (PMID 39932316, 2025). "To verify that donor NK cells exhibit similar CXCR3-dependent localization in recipient mice after infection, we transferred CD45.2+ NK cells from the spleens of C57BL/6 or Cxcr3-deficient (Cxcr3 KO) mice into JAXBoy (CD45.1+) recipient mice." (PMID 40694683, 2025). "Thus, infection is associated with prolonged activation of innate or expansion of adaptive immune populations in tonsils/adenoids, which may contribute to the generation of CXCR3+ BSM." (PMID 40964019, 2025). "As previously reported, approximately 50% of TREG cells in the spleens of LCMV-infected mice expressed CXCR3 on day 12 post-infection." (PMID 40478934, 2025). "CXCL19, as a chemokine, activates the MAPK pathway through its receptor CXCR3, further promoting immune cell migration to the infection site." (PMID 40427458, 2025). "This was corroborated by assessment of polyclonal CD11ahi CXCR3+ CD4+ T cells at 7-days post-infection (Fig 1Bi-ii)." (PMID 40132035, 2025). "Using this system, we confirm that CXCR3 re-positions NK cells in the white pulp of the spleen after infection, which is vital for immunoregulation." (PMID 40694683, 2025). "Yet, our data additionally indicate that CXCR3 is dispensable for the general accumulation of NK cells in the spleen during infection." (PMID 40694683, 2025). "We use this system to define the necessity of the chemokine receptor CXCR3 and the migration-associated factor ASCL2 in the enrichment of NK cells in the splenic white pulp after infection." (PMID 40694683, 2025). "On day 4 post infection, we found that in our model, Cxcr3 transcript levels were decreased in both infected Cxcl10+/+ and Cxcl10−/− mouse lung relative to the uninfected controls." (PMID 39803542, 2024). "According to some authors, the host positively regulates the transcription of chemokines, and CXCR3-expressing cells are expanded after infection." (PMID 39330908, 2024).
infection (continued). "This impairs signaling and chemotaxis in CXCR3-dependent cells, which is important for controlling infection as these cells shape the protective immune response." (PMID 39330908, 2024). "CXCR3 also recruits cytotoxic CD8+ T cells that contribute to clearance of infection, potentially including host cells harboring intracellular S. aureus." (PMID 38846955, 2024). "CXCR3 expression in γδ T cells significantly decreased after infection, indicating ligand interaction." (PMID 39211036, 2024). "In particular, the gamma interferon (IFN- γ) inducible chemokines CXCL9, CXCL10, and CXCL11, and their receptor CXCR3, are involved in T cell and macrophage recruitment to the site of infection." (PMID 39301034, 2024). "On the other hand, other chemokines involved in T cell trafficking such as Cxcl9 and Cxcl10 are highly expressed during the first few days of infection, as is their receptor Cxcr3." (PMID 38352492, 2024). "In fishes, the role of CXCR3 in macrophage recruitment to the site of infection has been studied in zebrafish." (PMID 39301034, 2024). "Group I showed greater numbers of all CCR6+ B-cell subsets and CXCR3+ naive B cells and plasma cells than did Group C. Infection of the nurslings promoted increased CCL20, CXCL10, IL-6, IL-8, total IgA, and IgG levels in the milk." (PMID 39867906, 2024). "In support of this concept, consistent elevation of CSF IP-10 levels compared to plasma throughout infection signifies a CNS environment primed for CXCR3-IP-10 mediated T cell ingress." (PMID 38060615, 2023). "CXCL10 is a chemokine known to chemoattract CXCR3-positive cells, including activated T cells, NK cells, macrophages (microglia cells in CNS), and dendritic cells, toward sites of infection and inflammation." (PMID 37235332, 2023). "Serving as chemokines, CXCL9, CXCL10, and CXCL11 attract the cells with their cognate receptor CXCR3, including neutrophils, monocytes/macrophages, dendritic cells, T cells, and NK cells, to the site of infection." (PMID 37214455, 2023). "Cxcr3 promotes effector T cell (TEFF) fate at the expense of central memory T cells (TCM) following a primary immune response to infection." (PMID 36472588, 2023). "Together our data suggest that IMs play an important role in recruiting CD4+ T cells to the foci of infection via the CXCL9/CXCR3 axis and provide an important source of IL-12 for maintaining Th1 cells." (PMID 37733817, 2023). "The expression of several genes was downregulated following infection, including the chemokine receptor CXCR3 as well as pattern recognition receptors FPR2 and TLR4." (PMID 37138882, 2023). "The spike-specific memory B cells generated by natural infection and vaccination was efficiently reactivated by spike-specific CXCR3+ TFH cells and CXCR3− TFH cells to differentiate into ASCs and produce spike-specific antibodies." (PMID 37802996, 2023). "The IFNγ-inducible chemokine receptor CXCL10 expressing myeloid cells recruit CXCR3 expressing activated Th1 lymphocytes to the sites of infection/inflammation." (PMID 38006039, 2023). "In mammals, G protein-coupled CXC chemokine receptor 3 (CXCR3) signalling is required for recruiting macrophages to the site of injury/infection." (PMID 36271843, 2023). "The proportion of CXCR3+CCR5+ CD4 T cells remained constant with infection, while there was a relative decline in these cells in the spleen during the acute phase." (PMID 38060615, 2023). "It has been shown that CD103n CD8+ Trm cells can be derived from CXCR3-dependent recruiting cells within inflamed areas and play a critical role in controlling infection." (PMID 36881472, 2023). "In single cells gated from two biological donors, the average frequency of CD19+/CXCR3+/CD11c-/+/FCRL4+ gated cells was 38.6 ± 15.7% at day 8 post-infection compared to 9.8 ± 3.2% of cells prior to infection (n = 2 LCLs, two-tailed Welch’s t-test p = 0.224)." (PMID 36248899, 2022).